USP22 (ubiquitin specific peptidase 22)
Diseases named in the same sentence as USP22 in open-access papers (continued):
Sharing a sentence is not in itself a finding about the gene and the disease.
cancer (continued). "Notably, we herein found that compared with the parent cancer cells, USP22 knockout cell were much more sensitive to irradiation, indicating therapeutic implication of targeting USP22 as an approach to combine with other conventional treatment." (PMID 31842906, 2019). "RNAseq data analysis showed that more than 2000 genes are differentially expressed in two USP22−/− cancer cells, and about 300 and 484 genes were unanimously upregulated or downregulated in two USP22−/− cancer cells (P < 0.01, false discovery rate: FDR < 0.05, log2 fold change: log2 FC ≥ 1)." (PMID 31842906, 2019). "Both RNAseq analysis and in vivo xenograft experiments demonstrated that USP22 may play an important role in cancer angiogenesis." (PMID 31842906, 2019). "The expression of USP22 is correlated with poor prognosis of several cancers." (PMID 30918246, 2019). "USP22 is also considered a marker of metastasis, it induces autophagy and promotes the survival of cancer cells especially in pancreatic cancer enhancing cell proliferation and resistance to chemotherapy under special conditions such as nutrient deprivation or hypoxia." (PMID 30524288, 2018). "Actually, USP22 has been identifiedas one of the putative cancer stem cell markers." (PMID 30088609, 2018). "If such a mechanism regulates USP22 in cancer, it may potentially explain why USP22 overexpression is more frequently observed via IHC than mRNA sequencing." (PMID 29210986, 2017). "This suggests that USP22 expression may be tightly regulated and that deviations, either as increases or decreases, have functional implications for cancer development and progression." (PMID 29210986, 2017). "Two subsets of cancers appear to coexist; those with increased USP22 expression and those with reduced expression, both of which may contribute to oncogenesis." (PMID 29210986, 2017). "Accordingly, these data suggest that USP22 may be a haplo-insufficient tumor suppressor gene, whose diminished expression may also contribute to cancer development." (PMID 29210986, 2017). "Owing to its relationship with the chemotherapeutic resistance of several types of human cancers, cyclin B1 may also mediate the USP22‐induced MDR in HCC cells, which is valuable for future exploration." (PMID 28417539, 2017). "Accordingly, this review will present the current knowledge regarding USP22 expression in cancer and describe how both increased and diminished USP22 expression may promote oncogenesis." (PMID 29210986, 2017). "Therefore, reduced USP22 expression cannot systematically induce cell cycle arrest and hinder cancer progression, as suggested above." (PMID 29210986, 2017). "Indeed, gene sequencing and mRNA expression data reveal that USP22 is more frequently deleted, mutated or underexpressed than amplified or overexpressed in those same cancer types for which IHC studies found USP22 to be overexpressed." (PMID 29210986, 2017). "If the function of USP22 in DSB repair is conserved in other cell types, then the loss of USP22 may prevent correct DSB repair and promote the accumulation of pathologic mutations underlying the development of cancer." (PMID 29210986, 2017). "While it is clear that USP22 is overexpressed in various cancer types and may promote oncogenesis by altering gene expression, cell death and cell cycle progression, emerging evidence suggests that USP22 also harbors tumor suppressor-like properties." (PMID 29210986, 2017). "Involvement of GCN5, USP22 and other submodules of SAGA have been linked with various cancers." (PMID 28415621, 2017). "Recent studies reported that overexpression of USP22 may be involved in the drug resistance of cancer through a variety of mechanisms." (PMID 28567015, 2017). "Recent emerging data now implicate USP22 and H2Bub1 as key regulators in many of these processes, and thus, hypomorphic USP22 expression may contribute to the development of genomic instability and promote cancer progression." (PMID 29210986, 2017).
cancer (continued). "In this study, we analysed eleven death-from-cancer signatures in survival of cancer patients and demonstrated that USP22 plays vital roles in gastric CSC self-renewal and GC progression by stabilizing BMI1 and regulating the expression of stemness genes such as CD133, SOX2, OCT4 and NANOG." (PMID 28415621, 2017). "Remarkably, reduced USP22 expression occurs more frequently than overexpression in many cancer types suggesting diminished expression and function may also be oncogenic." (PMID 29210986, 2017). "Eleven Polycomb/stem cells genes, including USP22 were identified as death-from-cancer signatures from transgenic mouse models and cancer patients and could predict poor therapeutic outcome in multiple cancers." (PMID 28415621, 2017). "Therefore, in cancer, USP22 up regulation leads to the abnormal activation of multiple pathways that are directed to cell survival." (PMID 27057639, 2016). "In addition, the expression of BMI-1, a biomarker of cancer stem cells, was remarkably repressed in USP22 knockdown cells." (PMID 27145278, 2016). "USP22 deubiquitylates histone and non-histone substrates and has been associated with cancer progression and spinocerebellar ataxia." (PMID 27057639, 2016). "In fact, elevated USP22 expression can predict shorter intervals of tumor recurrence, distant metastasis, therapeutic failure and poor prognosis in patients with many types of cancer, including colorectal, breast, and gastric cancers." (PMID 25909224, 2015). "Currently, we are developing small molecule inhibitors to target USP22 in cancer treatment." (PMID 27030811, 2015). "Notably, USP22 was initially reported as a member of an 11-gene “death from cancer” gene expression signature which identified tumors displaying a stem cell-like gene expression profile characterized by high malignancy and metastatic dissemination." (PMID 26431380, 2015). "USP22 has also been identified as a death-from-cancer signature gene." (PMID 27030811, 2015). "USP22 is involved in oncogenesis due to its role in a large variety of cancers." (PMID 25605410, 2015). "Particularly, results from two research groups in 2012 demonstrate that the USP22 level is increased and associated with overall survival in NSCLC patients, as well as patients with early-stage NSCLC, implying the involvement of USP22 in this specific type of cancer." (PMID 25547493, 2014). "The results showed that USP22 was clearly increased in 6 out of 20 analyzed cancer tissues." (PMID 24466336, 2014). "USP22 was mainly expressed in the nucleus of the cancer cells, and occasionally in the cytoplasm." (PMID 24466336, 2014). "Recent research advances have linked deregulation of USP22 to specific types of cancer, including NSCLC; however, the functional role of USP22 and its underlying mechanisms of action in cancer development are not well defined." (PMID 25547493, 2014). "Nevertheless, the potential molecular mechanism between increased USP22 expression and cancer metastasis in SACC is still unknown." (PMID 24466336, 2014). "We collected tissue samples representative of the OSCC spectrum including normal mucosa, carcinoma, and lymph node, to reveal whether alterations of USP22 expression may affect malignant transformation." (PMID 22880026, 2012). "Therefore, it is hypothesized that USP22 promotes cancer progression in BC cells by stabilizing c-Myc to promote apoptosis." (PMID 40083330, 2025). "This suggests that USP22 could serve as a novel tumor marker for cancer prognosis." (PMID 39048965, 2024). "USP22 was initially identified as a member of a so-called "death-from-cancer" gene expression signature, comprising a group of genes whose expression strongly correlated with cancer aggressiveness, poor response to currently used therapies, tumor relapse and diminished patient survival." (PMID 38347585, 2024).
cancer (continued). "The Ubiquitin Specific Peptidase 22 (USP22) is a deubiquitinase that has been frequently associated with a CSC-promoting function and intimately implicated in resistance to conventional therapies, tumor relapse, metastasis and overall poor survival in a broad range of cancer entities, including BC." (PMID 38347585, 2024). "These contradictory functions of USP22 may be due to the different cancer microenvironments." (PMID 39143031, 2024). "Hence, USP22 plays a critical role in immune evasion in human cancer cells." (PMID 38638430, 2024). "Therefore, we speculated that USP22 could influence malignant tumor phenotypic transformation by regulating EV secretion." (PMID 39101247, 2024). "Importantly, increased USP22 expression leads to significant activation of downstream signal pathways including H2Bub1 and c-Myc, which may potentially enhance cancer malignancy and counteract the anticancer efficacy of USP7 inhibition." (PMID 37946202, 2023). "However, in murine cancer models, Usp22 exerted both pro-oncogenic and anti-oncogenic effects." (PMID 37896966, 2023). "Importantly, our unbiased analysis of existing public database revealed a statistically significant positive correlation between USP22 and ITGB1 in 37 total human cancer types, suggesting that the USP22-FoxM1-integrin b1 axis is a common mechanism in CSC self-renewal." (PMID 37398311, 2023). "Besides, MDM2 inhibitor enhanced the antipancreatic cancer effect of USP22 overexpression." (PMID 34743406, 2022). "Since stromal cells can promote tumor growth and influence cancer behavior, we speculated that high expression of USP22 and EGFR suggested a higher degree of stromal cell infiltration in the TME, indicating a worse prognosis, and the K-M curve verified our hypothesis." (PMID 35899194, 2022). "However, USP15 is the same as USP22 in that its role in cancer depends on the environment." (PMID 34179009, 2021). "However, the importance and functional role of USP22 in different types and subtypes of cancer remain largely unknown." (PMID 34007022, 2021). "Moreover, USP22 protects cancer cells by enhancing autophagy." (PMID 33919439, 2021). "Knock-down and overexpression studies in cancer cell lines suggest that Usp22 may promote cancer through the positive regulation of well-known oncogenes including BMI1, c-MYC, SIRT1, cyclin B1, and KDM1A, mainly through the regulation of cell cycle progression." (PMID 34503086, 2021). "Noteworthy, USP22 also modulates the stability and function of multiple non-histone targets associated with cancer progression and poor prognostic outcome including c-Myc, Cyclin D1, Cyclin B1, EGFR, SOS, SIRT1, COX2, XPC, KDM1A, ERa, SHH, as well as nodal immunologic factors." (PMID 34007022, 2021). "Therefore, clarifying the roles of USP22 in cancer is critical to determine whether direct USP22 targeting will be beneficial for patients." (PMID 32063746, 2020). "However, recent studies have challenged the tumorigenic properties of USP22 in cancer." (PMID 32063746, 2020). "Consequently, USP22 is frequently hailed as an attractive target for cancer therapeutics." (PMID 30781493, 2019). "Our findings reveal that USP22 plays a critical oncogenic role and represents a potential therapeutic target in NSCLC, and targeting USP22 will bring broad antitumor effects through suppression on multiple signaling pathways associated with cancer progression, which warrants further study." (PMID 31842906, 2019). "Unfortunately, however, a USP22-specific inhibitor remains to be identified and, thus, an attractive alternative may be to employ synthetic lethality, a strategy that selectively targets cancers with genetic defects in cancer-promoting genes." (PMID 30781493, 2019). "Thus, reduced USP22 expression may induce chromosome instability and promote cancer development and progression." (PMID 30781493, 2019).
cancer (continued). "Moreover, synthetic lethal strategies have the unique benefit of enabling targeting of loss-of-function alterations, which would be relevant for cancer types frequently exhibiting reduced expression of E3 ubiquitin ligases (e.g., RNF20 or RNF40) or DUBs (e.g., BAP1 or USP22)." (PMID 30781493, 2019). "Interestingly, it was demonstrated that silencing USP22 inhibited proliferation in bladder cancer cells leading to cell cycle arrest, inhibition of autophagy and decreased tumor progression representing a potential target for cancer therapy." (PMID 30524288, 2018). "However, emerging data indicate that USP22 expression is more frequently downregulated in many cancer types, suggesting it may also harbor tumor-suppressor properties." (PMID 29210986, 2017). "However, gene re-sequencing data from numerous cancer types show that USP22 expression is frequently diminished, suggesting it may also harbor tumor suppressor-like properties." (PMID 29210986, 2017). "Notably, shallow deletions of USP22 occur frequently in ovarian (84% of cases), esophagus (46%), colorectal (44%), pancreatic (41%), lung adenocarcinoma (38%), breast (34%) and stomach (31%) cancers." (PMID 29210986, 2017). "USP22 upregulation may thus inhibit apoptosis and stimulate autophagy in response to treatment with DNA damaging agents or targeted inhibitors to promote resistance to chemotherapy in cancer patients." (PMID 29210986, 2017). "Indeed, alteration of the cell cycle checkpoints is a frequent feature of cancer cells, which may modulate the effects of USP22 overexpression and silencing in those cellular models." (PMID 29210986, 2017). "Furthermore, USP22 has been considered to be a proto-oncogene because its expression is significantly upregulated in malignant tumors of several tissues, including the cervix, colon and liver, and it participates in regulating proliferation, metastasis and recurrence." (PMID 28445968, 2017). "Nevertheless, significant evidence is accumulating that indicates USP22 expression promotes cell cycle progression in certain cancer cell lines and that USP22 overexpression may enhance proliferation of cancer cells by facilitating premature transition through various cell cycle stages." (PMID 29210986, 2017). "Thus, targeting USP22 might be an effective and convenient approach to treat cancers with high levels of CCNB1 expression." (PMID 27030811, 2015). "Overall, the findings presented here further support an important biological function of Usp22 and underscore the need for further in vivo and mechanistic studies to fully decipher its mechanisms of action and possible relevance as a therapeutic target in cancer." (PMID 26431380, 2015). "Previous and recent data suggested that both USP22 and CCNB1 are members of these signature gene families, the upregulation of which is associated with the development, progression and metastasis as well as chemotherapeutic resistance of several types of human cancers." (PMID 27030811, 2015). "Thus, USP22 is possibly involved in promoting cancer cell growth through multiple mechanisms." (PMID 27030811, 2015). "Interestingly, the Ubp8 homolog USP22 has been identified as a member of an 11-gene “death from cancer” signature that acts as a predictor of tumor aggressiveness, treatment resistance, and metastatic probability in cancer patients." (PMID 24948786, 2014). "Thus, our results supported this hypothesis that cancer cells expressing USP22 may manifest a stem cell-like characteristics such as therapy-resistant and metastasis-enabling phenotypes." (PMID 22880026, 2012).
cancer (continued). "At least five DUBs were reported to stabilize PD-L1 in different cancers, including USP7, USP9X, USP22, CSN5 and OTUB123,37–40." (PMID 38167274, 2024). "By silencing USP22, which plays a role in drug resistance, this co-delivery system sensitized HCC cells to Sorafenib, allowing more effective cancer cell apoptosis and improved overall treatment outcomes." (PMID 39741633, 2024). "Cancer cells express proteins such as sortilin, tribbles homolog 3 protein (TRIB3), and ubiquitin specific peptidase 22 (USP22), which suppress EGFR degradation via EGFR stabilization, and their knockdown inhibits cancer cells." (PMID 38745775, 2024). "Several DUBs, including USP10, USP18, USP22, USP43, and USP51 have been identified as key regulators of ZEB1 stability, thereby promoting proliferation, migration and invasion of cancer cells across different malignancies." (PMID 39736693, 2024). "USP22, a member of the USP family, acts a pivotal role in the cancer‐related death signature and primarily regulates cancer progression through its deubiquitinase activity." (PMID 39135915, 2024). "The recent report of novel USP22 specific inhibitors provides strong impetus for fully understanding the functions of this DUB in both normal cells and in cancers." (PMID 38236941, 2024). "Recent studies have reported that the overexpression of DUBs such as Cezanne-1, USP22, and USP25 in cancer cells prevents EGFR degradation." (PMID 39048965, 2024). "We recently identified that transcription factor SP1 is an inhibitor for USP22 gene expression, and here we found that FT671 treatment induced a significant decrease of SP1 protein in both A549 and H1299 cancer cells." (PMID 37946202, 2023). "On the other hand, several deubiquitinating enzymes, including ubiquitin-specific peptidase 7 (USP7), USP22, OTUB1, and CSN5, stabilize PD-L1 protein in cancer cells." (PMID 38038129, 2023). "The reported deubiquitinases of MYC include USP22, USP28, USP29, USP36 and USP37, and they enhance cancer stemness via BMI1, LSD1 Snail and CEP63 stabilization, respectively." (PMID 36765885, 2023). "The mutation rates of copy number variations (CNV) and the expression levels of mRNA were found to be positively correlated in most necroptosis-related genes in 33 cancer types, especially in the cases of FADD and USP22." (PMID 37000317, 2023). "These DUBs (USP22, USP28, USP29, USP36, USP37 and OTUD6A) are observed in stabilizing MYC in cancer cells." (PMID 36765885, 2023). "In support of this idea, several cancer cells overexpress EGFR-stabilizing proteins, such as Sortilin, TRIB3, and USP22, which suppress EGFR degradation, and their knockdown inhibits cancer cell proliferation." (PMID 36410436, 2022). "In summary, we identified a previously undescribed signaling pathway of the USP22-PPARγ-ACLY/ACC axis that plays an important role in lipogenesis and HCC tumorigenesis and provides an option for cancer therapy targeting fatty acid synthesis." (PMID 35449157, 2022). "Ubiquitin-specific protease 22 (USP22) can act as a deubiquitinating enzyme and exhibit its implication in oncogenesis due to regulation of proliferation, cell cycle, apoptosis, cancer stemness and chemoresistance." (PMID 35692754, 2022). "USP22, the deubiquitinating subunit of the SAGA transcriptional cofactor complex, is a member of an 11‐gene ‘death‐from‐cancer’ signature." (PMID 34743406, 2022). "USP22 is a functional mediator necessary for MYC to promote cancer and can increase the stability and tumorigenic activity of MYC in cancer cells." (PMID 35935969, 2022). "USP22 directly interacts with PALB2 to promote DNA homologous recombination repair and inhibit the killing effect of cisplatin on cancer cells." (PMID 35935969, 2022). "Ubiquitin-specific-processing protease 22 (USP22) has been recognized to promote EMT process and metastasis via activating FAK and repressing anti-cancer immunity in PaC." (PMID 33799952, 2021).